ESR1 (estrogen receptor 1)
Diseases named in the same sentence as ESR1 in open-access papers (continued):
Sharing a sentence is not in itself a finding about the gene and the disease.
tumor (continued). "Higher ESR1 gene amplification is found in BC with CCND1 gene amplification in comparison with tumours without CCND1 gene amplification." (PMID 26391647, 2015). "While we observed some intriguing associations among the underweight, including lower expression of ESR1 and PGR and being more likely to have a Basal-like tumor, we were limited by the small number of underweight women in our cohort (n = 13) to draw any definitive conclusions about this subgroup." (PMID 25884832, 2015). "Similar to these results, both the expression of Esr1 in tumor cells and lack of estrogen-dependent growth were observed when PyMT was targeted to mammary glands through intraductal injection of a modified avian retroviral vector." (PMID 26429062, 2015). "Independent adverse prognostic significance was retained in multivariable analysis for absence of necrosis, tumour ESR1 expression in all patients and low tumour mIS in stage III right-sided CRC." (PMID 25970543, 2015). "For ESR1-negative/HER2-positive tumors the amount of HER2 mRNA is not further relevant for response once a tumor is in the HER2-positive group." (PMID 23391338, 2013). "For ESR1-positive/HER2-positive tumors the situation is different; HER2 mRNA has a more continuous distribution and the response to neoadjuvant trastuzumab/chemotherapy rises continuously with the amount of HER2 mRNA within the HER2-positive tumor group." (PMID 23391338, 2013). "Similarly to Ar, Esr1 and Pr expression was significantly reduced in MMTV-NeuNT tumors compared to non-tumor bearing mammary glands." (PMID 23593223, 2013). "Tumor immunophenotype was determined for ESR1 (44 positive, 16 negative), PGR (35 positive, 25 negative), and ERBB2 (19 scored as negative or 1+, 11 scored as 2+, 11 scored as 3+ and 19 were not assayed)." (PMID 23936250, 2013). "ESR1 was uncommonly methylated and the p16 gene was not methylated in either tumor or non-cancerous breast tissues." (PMID 22701537, 2012). "None of the 15 known or supposed markers for CTC detection was considered for further investigations either due to detectable expression levels (ERBB2, ESR1, SERPINE1, SERPINE2 and FN1) in healthy controls or due to inadequate gene expression in the tumor cell lines." (PMID 21129172, 2010). "All of the ESR1-negative BRCA1 tumours with low expression of NFκB originated from BRCA1 truncating mutations that probably led to a complete absence of the protein through the nonsense-mediated mRNA decay mechanism (NMD)." (PMID 19826428, 2009). "Analysis of genes differentially expressed in ESR1-negative BRCA1 tumours revealed over-representation of genes involved in the immune response and cell cycle." (PMID 19826428, 2009). "PMR values of APC (r=0.398, P=0.001), RASSF1A (r=0.551, P<0.001), but not of ESR1 (r=0.078, P=0.52), were positively correlated with levels of the tumour marker CA15.3." (PMID 19367284, 2009). "Overall, 52 genes in gene-set #2 with annotations from these processes were identified and most were over-expressed in the ESR1-negative BRCA1 tumours." (PMID 19826428, 2009). "It is worth noting that all of the ESR1-negative BRCA1 tumours in group A, which show low expression of NFκB, harboured truncating mutations in the central portion of BRCA1 that are thought to trigger the nonsense-mediated mRNA decay mechanism." (PMID 19826428, 2009). "In our series the over-expression of genes related to immune response is one of the intrinsic characteristics of ESR1-negative BRCA1 tumours." (PMID 19826428, 2009). "Sixty percent of the tumours analysed here showed low or no expression of ESR1 or over-expressed genes typically found in basal-like tumours, whereas the remaining tumours showed over-expression of ESR1 and a nonbasal-like phenotype." (PMID 19826428, 2009). "In addition to the major classification mediated by ESR1 or basal markers, this study reveals further complexity of BRCA1 tumours." (PMID 19826428, 2009).
tumor (continued). "Applying a FDR of 1 out of 1000, 212 genes were differentially expressed within the class of ESR1-positive tumours (hereafter, gene-set #1) and 670 genes differentially expressed within the class of ESR1-negative tumours (gene-set #2) (respectively)." (PMID 19826428, 2009). "Moreover, gene expression levels of ESR1/ERα (P = 0.004), BCL2 (P = 0.003), and FOS (P = 0.01) were significantly lower in grade III (n = 11) than in grade I + II (n = 22) tumor samples." (PMID 18928543, 2008). "Indeed, ER+ tumours were scattered in subgroups 1 to 4 that are characterised by the over-expression of a cluster of genes, which includes CCND1, KRT19, IGF1R, LIV1, ESR1, GATA3, TFF1/pS2, ERBB4, PR and IGFBP4." (PMID 17338809, 2007). "We clearly see a discrimination between tumours highly expressing genes of the luminal/ESR1 cluster and tumours negative for these genes, whereas the discrimination for the HER2-overexpressing groups was much less clear." (PMID 17069663, 2006). "The expression analysis showed that ESR1 had no expression difference between normal and tumor groups; BCL2 expression was lower in tumor group (P < 0.001); while AKT1, CCND1, and HIF1A expressions were higher in tumor group compared with those in normal group (all P < 0.001)." (PMID 40552073, 2025). "Moreover, in DNA methylation alterations of tumor cells induced by GLP-1RAs, studies have demonstrated that during breast cancer progression, tumor suppressor genes such as ESR1, CDH1, and ADAM33 are downregulated due to hypermethylation alterations in their promoter regions." (PMID 40140925, 2025). "The loss of RB1 function and high levels of CCNE1 expression resulted in a decrease in ESR1 and PRG expression levels and hormone-dependent reactivity, which demonstrates that RB1 status is related to the growth and proliferation of hormone-dependent tumor cells." (PMID 39544302, 2024). "These clinical observations justify that, in tumors, an estrogen-induced amplification of the ESR1 gene is not a pro-oncogenic adaptation, but rather, an abundant expression of ERs may facilitate tumor responses." (PMID 39329990, 2024). "ERα is a potent driver of the proliferation and progression of ER-positive breast cancer, and, thus, this lower expression of ESR1/ERα may lead to a less aggressive tumor progression and, hence, a favorable prognosis." (PMID 36831182, 2023). "A luminal B tumor is an aggressive and proliferative subtype, which might not be solely dependent on ESR1 signaling." (PMID 37894401, 2023). "Thus, we investigated EDI3’s potential clinical relevance using publicly available data, as well as our own breast cancer patient cohorts, and show that EDI3 expression is highest in estrogen receptor (ESR1)-negative (ER-) HER2 + tumours." (PMID 36670508, 2023). "In general, the ESR1 variant with the highest VAF was the mutation that remained detectable in patients with polyclonal ESR1 mutations, suggesting the decline in VAF is a reflection of decreasing tumor load rather than a differential response." (PMID 37226020, 2023). "However, we identified a small triple positive (ERBB2 + /ESR1 + /PGR + (HER2 + /ER + /PR +)) DCIS region located in proximity to adipocytes which consisted of a predominantly DCIS #2 tumor epithelium without a KRT15+ myoepithelial cell layer." (PMID 38114474, 2023). "However, percentage of immunopositive cells for ESR1 in treated tumours was lower but not very significant compared to the tumours of control." (PMID 35386216, 2022). "Thus, it is plausible that ESR1 expression may inactivate the YAP pathway, resulting in suppression of cell cycle-related genes and tumor progression." (PMID 34145394, 2021).
tumor (continued). "Consequently, the F2P Score was established based on the combination of six genomic variables (ESR1, PGR, CD68, BAG1, BCL2, and GSTM1) and two clinicopathological variables (age and categorical tumor size) with the shrinkage factors of 0.314 and 0.888, respectively." (PMID 33042787, 2020). "Thus, using the TCGA database, we analyze ESR1 and ESR2 mRNA expression in tumor tissues." (PMID 32536040, 2020). "This difference could be explained by the decrease in oestrogen signalling in the HER2− tumours being in part dependent on the lower ESR1 levels on-treatment and not just by the oestrogen deprivation with the AI." (PMID 31892336, 2019). "As expected, expression of the oestrogen (ESR1)/progesterone (PGR) and HER2 (ERBB2) genes were highest in the luminal and HER2-enriched subtypes respectively, and as shown by others, expression of PGR was lower in luminal B tumours relative to luminal A (“PGR”, P < 0.001)." (PMID 30819233, 2019). "In this study, RYNXC could significantly decrease ESR1, PGR, EGFR, PTGS2, and Src mRNA expressions in a dose-dependent manner in MCF-10AT cells or breast precancerous lesion model rats, which could further inhibit cell proliferation and tumor progression." (PMID 30906412, 2019). "Notably, the biopsy (pre-treatment) and tumor samples (after treatment) obtained from all patients diagnosed with stage II were estrogen receptor ESR1-positive regardless of I2 supplementation." (PMID 31319484, 2019). "Differential analysis of tumor versus healthy biopsies highlighted 166 candidate genes with different DNA methylation levels in their promoters, which included the tumor-specific hypomethylated EGFL8 promoter as well as hypermethylated promoters of ESR1, PTGIS, and GATA3." (PMID 30645971, 2019). "Likewise, there was increased expression of ESR1 (ERα) mRNA in tumours with VI compared to tumours with no VI but was not significant (p = 0.07)." (PMID 29390981, 2018). "Tumour burden, ascites volume, and ascites incidence were not changed by E2 or Esr1 deletion." (PMID 29973689, 2018). "Nearly all of the 60 serous, mucinous, and endometrioid tumours examined were positive for either GREB1 or ESR1 (or both); only one tumour was negative for both markers, and notably, ESR1 staining was still observed in one of three scoreable cores from this tumour." (PMID 29973689, 2018). "Targeting GREB1 may inhibit tumour-promoting pathways both downstream and independent of ESR1 and is therefore a possible treatment strategy worthy of further investigation." (PMID 29973689, 2018). "However, knockdown of ESR1 and Δ133TP53 altered expression of all genes, unlike what was observed in the tumour analyses." (PMID 30018742, 2018). "In addition, CMT, like human BC, shows a negative correlation between estrogen hormone receptor ESR1 expression and increasing tumor grade." (PMID 30126376, 2018). "However, we detected a positive staining for ESR2 expression as a common event in OPSCC, while ESR1-positive tumor cells were a rather rare event (data not shown)." (PMID 28166815, 2017). "But, generally these miRNAs and their interaction with tumor gene or ESR1 are not studied enough." (PMID 28793339, 2017). "Receptor conversion from an ESR1-positive primary tumor to an ESR1-negative metastasis could not explain this finding." (PMID 28141868, 2017). "One possible explanation may lie in the fact that ESR1 activity depends on the presence of estrogen, which may not be universally available within the tumour." (PMID 27997592, 2016). "We next randomly selected 8 genes aberrantly expressed in HCCs that had aberrant DNA methylation (CR1, ESR1, PTPN13, and SOCS2) or SCNA (C8A, CXCL14, ITGA6 and MARCO) to validate the array-based results in an independent sample set consisting 47 HCCs and paired non-tumor specimens." (PMID 25965583, 2015).
tumor (continued). "In addition, both HER2 (r=0.547, P=0.001, data not shown) and HER4 (r=0.513, P=0.017) correlated positively with ESR1 expression levels in these HER2 non-amplified tumours including both pre- and postmenopausal women." (PMID 23991224, 2013). "Additionally, AQUA scores for ESR1 were compared for 2 independent cores from the YTMA 128 cohort (R2 of 0.74) and from the YTMA 130, (R2 of 0.54) illustrating the level of heterogeneity of ESR1 expression between different cores of the same tumor." (PMID 22606272, 2012). "While decreased ESR1 expression may initially decrease tumor growth, it is possible that these treatments may, in fact, enhance the formation of more aggressive ERα-negative tumors." (PMID 22913342, 2012). "Although the immune response gene-set is differentially expressed in the same direction in all ESR1-negative BRCA1 tumours examined here, it can stratify tumours in at least two additional subclasses depending on the magnitude of the expression of specific genes." (PMID 19826428, 2009). "In summary, in this study we have established the gene expression profiling of a series of BRCA1 tumours and found that there is a further degree of heterogeneity beyond the main classification by the expression of ESR1 and the presence or absence of a basal-like phenotype." (PMID 19826428, 2009). "In contrast, three of the five BRCA1 ESR1-negative tumours, which showed the highest levels of NFκB2 and RELB expression, harboured missense mutations that might led to an aberrant but still present BRCA1 protein." (PMID 19826428, 2009). "In addition to ESR1/ERα, the top-ranked genes selected by statistical cross-analyses were MET, FOS, SNCG, IGFBP4, and BCL2, which were subsequently validated in a larger set of tumor samples (from 17 control patients and 18 TF patients)." (PMID 18928543, 2008). "Among all selected prognostic biomarkers, ESR1, PGR, BRTC, YWHAQ and PLK1 were recognized as crucial features; for clinical features, whether the patient has gone through chemotherapy/hormone therapy and the size of the tumor play an important role in model predictions." (PMID 36698767, 2023). "Hence, for an example, ESR1 mRNA measurement by OncotypeDx and Prosigna from the same tumor may not correlate very well." (PMID 33579950, 2021). "Indeed, DNA methylation dependent gene silencing is frequent in BC and is highly related to BC tumor genotypes (e.g. hypermethylation of ESR1 in ERα negative patients), and may be essential to determine the good treatment." (PMID 26474850, 2015). "In contrast, 60% of the ESR1-negative tumours (group B), which show the highest expression of NFκB2 and RELB, harboured missense mutations in BRCA1, which could produce aberrant proteins but conserving some activities such as the capacity to activate the NFκB machinery." (PMID 19826428, 2009). "Strong immunoreactivity of ESR1, APOA1, IGF1, and PON1 was observed in normal tissues, whereas weak or no staining was observed in tumor tissues." (PMID 40317014, 2025). "Of particular note, while both ESR1 and PGR showed higher expression in non-recurrent tumours in the first 5 years of follow-up in METABRIC, neither showed a significant difference after 10 years in either METABRIC or VLR." (PMID 38709373, 2024). "Given that we observed downregulation of estrogen receptor 1 with the addition of CAF-conditioned media, it is possible that these CAFs represent the CD146 negative lineage shown to stimulate more aggressive tumor behavior." (PMID 37423299, 2023). "We observed that the Entinostat-mediated ESR1 downregulation was only partially, but not completely, rescued by deletion of VGLL3, suggesting Entinostat has broader anti-tumour effect." (PMID 35217640, 2022). "Tumour specimens treated with HSA presented a significant lower % expression of Bcl-xL, TNF-α, COX2, and ESR1 and compared to the specimens in the non-treated control group." (PMID 35386216, 2022).
tumor (continued). "The results of the present study revealed that the expression of ESR1 and PGR correlated with the tumor stage, whereas the expression of ESR2 did not." (PMID 34322374, 2021). "Discordant ER/ESR1 cases were predominantly STRAT4-ESR1 negative/IHC positive (11/12 cases) with weak and/or low expression of ER by IHC in mostly very small tumor areas tested (<25 mm2)." (PMID 34050358, 2021). "One possible explanation is that tumours can adapt to CDK4/6 inhibitors if ESR1 signalling is not correctly suppressed, but, when considering the lack of consensus regarding ESR1 status and CDKi sensitivity, further studies are needed." (PMID 34068388, 2021). "Crucially, HK2 prognostic value was independent of tumor proliferation as assessed by multivariate cox analysis using MKI67, ESR1 and HER2 expression levels." (PMID 32164162, 2020). "In contrast to the decrease in ESR1 levels seen in the HER2− tumours, in HER2+ tumours, ESR1 gene expression was not significantly changed (p = 0.009 for the difference between the groups)." (PMID 31892336, 2019). "Tumors exhibiting a myoepithelial PAM50 profile are referred to as basal-like tumours and are usually triple negative breast cancers (TNBC) in that they do not express ESR1 and PGR and do not have amplified HER2 expression." (PMID 30248920, 2018). "This allows ESR1+ tumours to achieve estrogen-independent growth and helps to explain why both XBP1 isoforms can drive ESR1+ cancer, but not TNBC." (PMID 30248920, 2018). "Both in-frame fusions from advanced disease, ESR1-e6>YAP1 and ESR1-e6>PCDH11X, promoted estrogen-independent growth (−E2), but the primary tumor fusion event, ESR1-e6>NOP2, had no growth-promoting properties." (PMID 30089255, 2018). "Irrespective of ESR1-status, we showed that APOBEC3B expression was increased in distant metastases compared to the corresponding primary tumor, with highest expression in liver, lung, brain and bone metastases." (PMID 28141868, 2017). "Concordance was 100 % for ERBB2, ESR1, PGR whereas for MKI67, one case containing 10 % tumor cells was negative in the non-macrodissected sample." (PMID 27389414, 2016). "When the variables were combined in a Cox proportional hazards multivariate analysis ER protein expression remained significant independent of age, tumor size, nodal status, PgR, HER2, and ESR1 status." (PMID 22606272, 2012). "The tumours positive and negative for ER, PR and HER2 showed a significantly different level of expression for their respective genes ESR1, PGR and ERBB2 (P<0.01, Welch's t-test)." (PMID 22067903, 2011). "Interestingly, the ESR1-negative tumours were substratified into two groups presenting slight differences in the magnitude of the expression of immune response transcripts and REL/NFκB transcription factors, which could be dependent on the type of BRCA1 germline mutation." (PMID 19826428, 2009). "However, hormone-related genes (BAG1, BCL2, CD68, ESR1 (ER), GSTM1, PGR, SCUBE2) do not show significant differential expression among all tumor samples." (PMID 38254834, 2024). "In the 12Z-ESR1 model, in which ESR1 was stably overexpressed, we did not explore the regulation of ESR1 by EZH2, although EZH2 expression is negatively correlated with ESR1 expression in patient tumor tissues." (PMID 35326450, 2022).